ACOT9 (acyl-CoA thioesterase 9)
Description:
Mitochondrial acyl-CoA thioesterase. Catalyzes the hydrolysis of acyl-CoAs into free fatty acids and coenzyme A (CoA), regulating their respective intracellular levels. Regulates both mitochondrial lipid and amino acid metabolism.
Synonyms: CGI-16; MT-ACT48; ACATE2; MTACT48
Tractability: Antibody: the Human Protein Atlas places it where antibodies can reach. PROTAC: ubiquitination databases record sites on it; its protein half-life has been measured.
Target class: Enzyme; Hydrolase
Gene: Protein-coding gene on chromosome X (23,699,396 to 23,766,475, reverse strand). Ensembl gene ENSG00000123130.
Subcellular location: Mitochondrion; Mitochondrion matrix; Mitochondrion inner membrane
Subcellular location (Human Protein Atlas): Cytosol; Plasma membrane; Nucleoplasm
Pathways (Reactome):
Metabolism: Mitochondrial Fatty Acid Beta-Oxidation
Gene Ontology:
Molecular function: acetyl-CoA hydrolase activity; fatty acyl-CoA hydrolase activity; long-chain fatty acyl-CoA hydrolase activity; medium-chain fatty acyl-CoA hydrolase activity; short-chain fatty acyl-CoA hydrolase activity
Biological process: acyl-CoA metabolic process; long-chain fatty acid metabolic process; short-chain fatty acid metabolic process; fatty acid metabolic process
Cellular component: mitochondrion; mitochondrial inner membrane; mitochondrial matrix
Homologues: Orthologues: chimpanzee ACOT9 (99% identical), macaque ACOT9 (98% identical), guinea pig ACOT9 (90% identical), dog ACOT9 (89% identical), mouse Acot9 (81% identical), pig ACOT9 (81% identical), rat Acot9 (81% identical), mouse Acot10 (79% identical), rabbit ACOT9 (78% identical), tropical clawed frog acot9 (68% identical), zebrafish acot9.1 (60% identical), zebrafish acot9.2 (59% identical), and 7 more.
Diseases named in the same sentence as ACOT9 in open-access papers:
ACOT9 is named in the same sentence as 11 diseases in open-access papers, as found by Europe PMC text mining. Sharing a sentence is not in itself a finding about the gene and the disease. The quoted sentences say what the papers report.
hepatocellular carcinoma (2 papers, 2022 to 2025). A malignant tumor that arises from hepatocytes. "A recent study found that ACOT9 promoted tumor metastasis and growth by reprogramming lipid metabolism pathways in hepatocellular carcinoma." (PMID 36568252, 2022).
Anxiety (1 paper, 2019). Intense feelings of nervousness, tension, or panic often arise in response to interpersonal stresses. "We find that tonic immobility shows no phenotypic correlation with inverted restraint behaviour; however, both PRDX4 and ACOT9 are also strong candidates for sociality/anxiety behaviour in the chicken." (PMID 31067744, 2019).
Cirrhosis (1 paper, 2026). A chronic disorder of the liver in which liver tissue becomes scarred and is partially replaced by regenerative nodules and fibrotic tissue resulting in loss of liver function. "In the human cirrhosis dataset (GSE254610), ACOT9 was also significantly upregulated, confirming its relevance to advanced human disease." (PMID 42292398, 2026).
colorectal cancer (1 paper, 2019). A primary or metastatic malignant neoplasm that affects the colon or rectum. "In human, CRNDE knockdown by siRNA in colorectal cancer cell lines leads to an under-expression of FASN, and an overexpression of ACADVL and ACOT9, two genes involved in lipid catabolism." (PMID 31752679, 2019).
Hepatic steatosis (1 paper, 2024). Steatosis is a term used to denote lipid accumulation within hepatocytes. "More recently, ACOT9, a mitochondrial enzyme of the ACOT family, was found to modulate hepatic steatosis." (PMID 39624175, 2024).
non-alcoholic fatty liver disease (1 paper, 2020). "According to a recent study, mitochondrial ACOT9 promotes substrate biosynthesis for lipogenesis and hepatic glucose production through directing acetyl-CoA toward the citric acid cycle, thereby aggravating non-alcoholic fatty liver disease." (PMID 33362855, 2020).
steatosis (1 paper, 2024). Increased lipid within the cytoplasm of cells. "However, ACOT9 rescue resulted in steatosis but not the development of MASH." (PMID 39624175, 2024).
tumor (2 papers, 2022). "Fat accumulation due to ACOT9 deficiency in tumor-associated macrophages may promote tumor growth and suppress immunity." (PMID 36291893, 2022).
endocrine system disorder (1 paper, 2010). A disease involving the endocrine system. "IPA data base showed RETNLB and FDPs were associated with endocrine system disorders; CAPG, ACOT9, FDPS, and IMPDH2 were associated with genetics disorder." (PMID 21172007, 2010).
ACOT9 also shares sentences with these, for which no sentence is quoted: laryngeal carcinoma (1 paper); liver fibrosis (1).